IFTAP (intraflagellar transport associated protein)
Description:
Seems to play a role in ciliary BBSome localization, maybe through interaction with IFT-A complex.
Synonyms: C11orf74; NWC; FLJ38678; HEPIS
Tractability: PROTAC: ubiquitination databases record sites on it.
Gene: Protein-coding gene on chromosome 11 (36,594,369 to 36,675,695, forward strand). Ensembl gene ENSG00000166352.
Subcellular location (Human Protein Atlas): Cytosol; Aggresome
Gene Ontology:
Molecular function: intraciliary transport particle A binding; protein binding
Biological process: acrosome reaction; spermatogenesis
Cellular component: 9+0 non-motile cilium; cytosol; ciliary tip
Genetic constraint (gnomAD): Loss-of-function variants: 12 observed, 12.84 expected, observed/expected ratio (o/e) 0.93, 90% interval 0.6 to 1.51. The upper end of that interval is the gene's LOEUF score, 1.51, which puts it in group 6 of 6, group 1 being the genes least tolerant of losing a copy. Missense variants: 213 observed, 223.83 expected, observed/expected ratio (o/e) 0.95, 90% interval 0.85 to 1.07. Synonymous variants: 76 observed, 75.39 expected, observed/expected ratio (o/e) 1.01, 90% interval 0.84 to 1.22.
Homologues: Orthologues: macaque IFTAP (90% identical), chimpanzee IFTAP (76% identical), pig IFTAP (68% identical), mouse Iftap (65% identical), rabbit IFTAP (63% identical), rat Iftap (60% identical), guinea pig IFTAP (60% identical), tropical clawed frog iftap (29% identical).
Diseases named in the same sentence as IFTAP in open-access papers:
IFTAP is named in the same sentence as 1 disease in open-access papers, as found by Europe PMC text mining. Sharing a sentence is not in itself a finding about the gene and the disease.
IFTAP shares sentences with these, for which no sentence is quoted: nevus (1 paper).